VCAM1 (vascular cell adhesion molecule 1)
Diseases named in the same sentence as VCAM1 in open-access papers (continued):
Sharing a sentence is not in itself a finding about the gene and the disease.
breast cancer (157 papers, 2007 to 2025). A primary or metastatic malignant neoplasm involving the breast. "A pH-sensitive drug release was achieved in response to acidic intracellular environments, reducing the expression of the metastasis-associated VCAM-1, thus inhibiting the migration of metastatic 4T1 breast cancer cells." (PMID 36678661, 2022). "Since then, the over-expression of VCAM-1 has been associated with metastasis in various adult-onset cancers, including breast cancer, gliomas, ovarian cancer and colorectal cancer." (PMID 36497180, 2022). "Using the results from the TCGA database, we found C1QBP mRNA levels in breast cancer tissues were associated with the levels of VCAM-1." (PMID 33708767, 2021). "The active targeting of the developed nanocomplexes to VCAM-1 and IL4Rα receptors were used as an effective therapeutic and diagnostic tool for murine breast cancer using noninvasive bioluminescence and Magnetic Resonance (MR) imaging." (PMID 32751068, 2020). "SPIC has also been shown to act as a lymphoid-specific enhancer and regulates VCAM1, a gene that has been associated with progression, angiogenesis, and metastasis in breast cancer." (PMID 32298355, 2020). "The interaction between the leukocyte α 4-integrins and VCAM-1 in breast cancer cells renders certain susceptible to pro-apoptotic signals." (PMID 32751068, 2020). "In summary, anti-VCAM1 and anti-IL4Rα aptamers specific to VCAM-1 and IL4Rα receptors biomarkers that are overexpressed in 4T1-Luc2 tumor bearing mice were used as diagnostic and therapeutic tools for breast cancer." (PMID 32751068, 2020). "Fourth, VCAM1 is highly expressed in breast cancer cells and recruits tumor-associated macrophages (TAMs) to the tumor microenvironment, triggering Akt activation in cancer cells and protecting cancer cells from cytokine-induced apoptosis." (PMID 28356139, 2017). "Clinically the activity of Src in breast cancer is correlated with bone metastasis whereas VCAM1 is associated with lung metastasis." (PMID 27486983, 2016). "Vascular cell adhesion molecule-1 (VCAM-1) promotes lung metastasis in breast cancer by tethering cancer cells to lung metastasis-associated macrophages." (PMID 25116261, 2014). "Elevated levels of the intercellular adhesion molecule-1 (ICAM-1) and vascular cell adhesion molecule-1 (VCAM-1) are found in stage IV breast cancer patients and are associated with worse prognosis." (PMID 23113882, 2012). "Chen and colleagues found that VCAM-1 on breast cancer CTCs tethered to metastasis-associated macrophages which express α4-integrins." (PMID 22837985, 2012). "Indeed, serum VCAM-1 levels have been associated with the microvessel density in breast cancer, and angiogenic signals have been described to stimulate VCAM-1 gene expression in endothelial cells." (PMID 39596815, 2024). "Moreover, vascular cell adhesion molecule-1 (VCAM-1) expressed in breast cancer cells has been associated with lung metastasis relapse." (PMID 33922795, 2021). "VCAM-1 has been implicated in the formation of macrometastasis of breast cancer cells." (PMID 31817646, 2019). "However, aberrant expression of VCAM-1 was found to be one of 18 signature genes associated with lung metastasis of breast cancer in both experimental mouse models and patients." (PMID 22837985, 2012). "This study documents variants of the N-glycosylation state of VCAM-1 that can be induced in normal endothelial cells exposed to tumoral soluble factors derived from human breast cancer cells that could contribute to cell-cell adhesion and hence to malignancy." (PMID 19930605, 2009). "With the combination of 2-DE and western blot techniques and the aid of tunicamycin, we analyzed N-glycosylation variants of VCAM-1 in primary human endothelial cells stimulated with either TNF or tumoral soluble factors (TSF's) derived from the human breast cancer cell line ZR75.30." (PMID 19930605, 2009). "In addition, VCAM-1 was also recently found to be associated with bone metastasis in breast cancer." (PMID 22837985, 2012).
breast cancer (continued). "To verify the role of VCAM1–VLA-4 interactions in human breast cancer, we profiled VCAM1 expression in cell lines and multiple patient-derived xenograft (PDXs) models (such as TN1 and CTC-derived model CTC-205) we generated." (PMID 40955669, 2025). "When α4-integrin on monocytes is engaged, VCAM-1 transmits anti-apoptotic signals to breast cancer cells through the PI3K/Akt pathway, promoting tumor cell survival." (PMID 40427136, 2025). "VCAM-1 is a prominent component of metastasis-specific gene signatures in breast cancer, playing a crucial role in modulating the metastatic processes." (PMID 40927361, 2025). "Similar findings revealed that LPS‐activated monocytes release TNF‐α to induce endothelial ICAM‐1/VCAM‐1 expression, thereby facilitating breast cancer cell adhesion and metastatic progression." (PMID 40747615, 2025). "We demonstrate that DPT-CTC clusters drive breast cancer metastasis via VLA-4 (ITGA4/B1)–VCAM1 interactions." (PMID 40955669, 2025). "VCAM-1-mediated VLA-4 binding recruits tumor-associated macrophages (e.g., in breast cancer metastases to the lungs)." (PMID 40927361, 2025). "The percentage of patients with positive VCAM1 expression in breast cancer tissues is increased, and the expression rate is greater in patients with lymph node metastasis." (PMID 38516703, 2024). "A recent investigation revealed that the recruited macrophages induced the PI3K/Akt survival signaling pathway in newly spread breast cancer cells by activating vascular cell adhesion molecule-1 (VCAM-1) through α4 integrins." (PMID 38397421, 2024). "A recent study in breast cancer cells reported that recruited macrophages trigger the PI3K/Akt survival signaling pathway by engaging vascular cell adhesion molecule-1 (VCAM-1) via α4 integrin." (PMID 39003350, 2024). "Compared with those in the model group, the expression levels of VEGFR2 and VCAM1 in breast cancer tissues were significantly decreased after SYF-H treatment." (PMID 38516703, 2024). "The administration of neutralizing VCAM-1 antibodies impairs breast cancer cell adhesion to endothelial cells, transmigration through endothelial monolayers and metastasis formation." (PMID 37773178, 2023). "The transmembrane glycoprotein VCAM-1 (CD106) on the surface of the breast cancer cell membrane mediates adhesion to leukocytes and the early stages of brain metastasis seeding by combining with integrin VLA-1 (α4β1)." (PMID 36895440, 2023). "According to the results of the study, VCAM1 seems to be the best potential marker of metastatic breast cancer, but should be validated by gene expression analysis in metastatic tissue samples where contamination by immune cells has been avoided." (PMID 37958607, 2023). "The elevated expression of GPNMB and VCAM-1 has beenobserved inmany cancers including breast cancer, melanoma, and prostate cancers.Such overexpression of GPNMB and VCAM-1 has been associated with poorprognosis and increased cancer metastasis." (PMID 37067377, 2023). "In fact, neutralizing VCAM-1 antibodies inhibit neutrophil and cancer cell infiltration and metastasis in in vivo models of breast cancer and melanoma." (PMID 37773178, 2023). "It has also been found that in vitro VCAM-1 knockdown in breast cancer cells reduces the proliferation and migration of IL-6-influenced breast cancer cells, thus increasing chemosensitivity." (PMID 36793444, 2023). "TNF‐α in breast cancer stem cells induces vascular cell adhesion molecule 1 (VCAM‐1) to promote angiogenesis, and the formation of PMN which is induced by breast‐liver organ crosstalk." (PMID 37902101, 2023). "VCAM-1 in the endothelium participates actively in the metastatic process in different types of cancer, including breast cancer, by promoting adhesion of tumor cells to the endothelium, transmigration through endothelial monolayers and metastasis formation." (PMID 37773178, 2023).
breast cancer (continued). "VCAM-1 is abnormally expressed in gastric cancer, renal clear cell carcinoma, melanoma, breast cancer, glioma, and other malignant tumours." (PMID 36979820, 2023). "Ectopic expression of VCAM-1 has been observed in breast cancer involving tumor-stromal interactions, angiogenesis, and metastasis." (PMID 36290384, 2022). "An example is the positive correlation identified in the up-regulation of the VCAM-1 gene with breast cancer metastases in lungs." (PMID 35742950, 2022). "Diminishing VCAM-1 expression of mammary tumors or blocking VCAM-1 and VLA-4 binding by anti-VLA-4 antibody decreases the lung metastatic potential of the breast tumor model." (PMID 36497180, 2022). "Similar interactions between VCAM-1 in metastatic breast cancer cells and VLA-4+ osteoclast progenitors have also been described in osteolytic lesions of metastatic breast cancer." (PMID 36497180, 2022). "Findings have shown that VCAM-1 and α4β1 integrin are individually expressed on vascular smooth muscle cells and endothelial cells in the developing vessels of breast cancer." (PMID 35347517, 2022). "It has been demonstrated that down-expression of the VCAM1 gene supports tumour growth in brain metastasis from breast cancer, which is in agreement with our findings." (PMID 35045088, 2022). "VCAM-1 is aberrantly expressed in breast cancer cells, and that it can bind to its natural ligand α4β1integrin, also denoted as very late antigen 4 (VLA-4)." (PMID 36482887, 2022). "Recent studies have shown that vascular cell adhesion molecule-1 (VCAM1) is aberrantly expressed in breast cancer cells and mediates prometastatic tumor-stromal interactions." (PMID 36497286, 2022). "Not only are soluble VCAM-1 and ICAM-1 elevated in the plasma of breast cancer patients, but higher VCAM-1 serum levels in patients with epithelial ovarian cancer were also linked with disease progression and metastasis." (PMID 35463298, 2022). "Here, we demonstrate that a VCAM-1–targeted imaging approach has the potential to better detect brain tumor margins, using preclinical models of breast cancer brain metastasis and glioblastoma, than currently used clinical MRI methods." (PMID 35312755, 2022). "Dormancy escape was also induced through the overexpression of vascular cell adhesion protein 1 (VCAM-1) in dormant, metastatic breast cancer lines residing in the bone marrow." (PMID 36430404, 2022). "C1QBP levels were associated with the expression of VCAM-1, P65 and HIF-1α in patients with breast cancer patients, especially in TNBC." (PMID 33708767, 2021). "Further analysis revealed that the expression of HIF-1α, along with VCAM-1 and P65 levels, correlated well with each other in breast cancer and TNBC tissues, and was in accordance with previous studies." (PMID 33708767, 2021). "Among them vascular cell adhesion molecule-1 (VCAM-1) is abnormally expressed in breast cancer cells and binds to α4β1 integrin, which further interacts with fibronectin." (PMID 33418894, 2021). "Previous research has indicated that VCAM‐1 contributes to breast cancer cells metastasizing to lung." (PMID 34427969, 2021). "Prolonged blood circulation, high tumoritropic accumulation, proactive recruitment capacity from CCL2/CCR2, and α4/VCAM‐1 active targeting property were achieved by QE‐loaded BS‐NPs@MφCM NPs, resulting in the inhibition of lung metastasis of breast cancer." (PMID 33898169, 2021). "MAMs expressing α4-integrins can promote breast cancer cell survival and metastatic growth via binding to the VCAM-1 on metastatic tumour cells." (PMID 35006432, 2021). "Pulmonary parenchyma containing collagen and elastin fibers acts as a favorable environment for homing of breast cancer expressing VCAM-1." (PMID 33418894, 2021). "During metastasis to the lungs in breast cancer, VCAM-1 recognizes the α-subunit, interacts with 4-integrin on monocytes, and enhances the formation of metastatic tumor cells in lung tissues." (PMID 33708767, 2021).
breast cancer (continued). "For instance, in a breast cancer model in mice, blockade of VCAM-1 reduced tumor LVI, presumably due to its role in destabilizing lymphatic endothelial junctions by engaging α4β1 integrin on adjacent LECs." (PMID 34685565, 2021). "Among malignant cells that enter such a quiescent state, metastatic breast cancer cells were noted to escape dormancy after vascular cell adhesion molecule-1(VCAM-1) upregulation." (PMID 35118073, 2021). "In osteolytic bone metastasis of breast cancer, aberrant expression of VCAM-1, in part dependent on the activity of the NF-κB pathway, promotes the transition from indolent micrometastasis to overt metastasis." (PMID 35006432, 2021). "In breast cancer cells, VCAM‐1 expression was up‐regulated in the selected cancer cells which metastasized to lung." (PMID 34427969, 2021). "VCAM-1 promotes the progression of tumors and plays an important role in the metastasis of breast cancer to the lungs, thereby making it a potential therapeutic target for inhibiting metastasis." (PMID 33708767, 2021). "Following infiltration of breast cancer cells to the leukocyte-rich microenvironment of the lung, VCAM-1 provides a survival advantage by tethering MAMs to cancer cells via counter-receptor α4 integrins." (PMID 33922795, 2021). "For instance, Min and colleagues found that VCAM-1 was overexpressed in metastatic breast cancer cells to lungs." (PMID 33103723, 2020). "Another mechanism that TAMs utilize to regulate breast cancer metastasis to the lungs is through the expression of α4 integrins of TAM that bind to VCAM-1 expressed by cancer cells." (PMID 32283687, 2020). "Short-term microgravity led to an increased synthesis of ICAM-1 and VCAM-1 proteins in MDA-MB-231 breast cancer cells during a parabolic flight campaign." (PMID 32013031, 2020). "One study showed that P2Y2R activation increased intracellular cell adhesion molecule-1 (ICAM-1) and vascular cell adhesion molecule-1 (VCAM-1) expression in a highly metastatic breast cancer cell line." (PMID 32635260, 2020). "The suppression of VCAM-1 on breast cancer cells prevents the formation of metastatic colonies in the lungs." (PMID 32751068, 2020). "Recently, an increasing number of clinical data proved that VCAM1 is abnormally expressed in gastric cancer, renal clear cell carcinoma, melanoma, breast cancer, glioma, and other malignant tumors, and is negatively correlated with the prognosis of patients." (PMID 32793471, 2020). "In the bone perivascular niche, α5β3 and α4β1 integrins are stimulated by von Willebrand Factor (VWF) and VCAM-1, respectively, from the endothelial cells and actively sustain chemoresistance of bone-disseminated breast cancer cells." (PMID 31963820, 2020). "The upregulation of vascular cell adhesion molecule 1 (VCAM-1) in tumor cells promotes the transition from indolent micrometastasis to overt metastasis in breast cancer." (PMID 32850317, 2020). "VCAM1 was overexpressed in lung metastasis compared to primary breast cancer and mediated bone metastasis in mouse and human breast cancer cell lines." (PMID 32793471, 2020). "Vascular cell adhesion molecular 1 (VCAM1), an important member of the immunoglobulin superfamily, is related to the development of malignant tumors, such as breast cancer, melanoma, and renal clear cell carcinoma." (PMID 32793471, 2020). "For example, Vascular Cell Adhesive Molecule-1 (VCAM-1) is seemingly expressed in the lung metastatic breast cancer cells and shows that it transmits pro-survival signals when macrophages are involved." (PMID 32751068, 2020). "Bone-latent breast cancer cells expressing VCAM-1 recruit α4β1 integrin-positive monocytic osteoclast progenitors that elevate local osteoclast activity favoring metastasis formation." (PMID 31963820, 2020). "It is now well-established from a variety of studies that VCAM1 is closely related to the development of malignant tumors, such as breast cancer, ovarian cancer, and clear cell renal carcinoma." (PMID 32793471, 2020).
breast cancer (continued). "During the metastasis of breast cancer, the cancer cells abnormally express vascular cell adhesion molecule-1 (VCAM-1) and infiltrate leukocyte-rich microenvironments; this is related to recurrence in the lungs." (PMID 32546174, 2020). "Antibodies against VCAM-1 and integrin α4 were also shown to inhibit breast cancer metastasis to the bone." (PMID 31817646, 2019). "Recent progress in breast cancer research has led to the identification of Vascular Cell Adhesion Molecule-1 (VCAM-1) as a key actor of metastatic colonization." (PMID 31340603, 2019). "Metastatic cells in the lung, from either mouse or human breast cancer, overexpress vascular cell adhesion molecule-1 (VCAM-1) and shRNA-mediated depletion of VCAM-1 inhibited metastasis formation." (PMID 31447834, 2019). "In breast cancer, the vascular-endothelial molecule-1 (VCAM-1) binds with high affinity α4β7 and α4β1 on OC precursors, leading to osteoclastogenesis, and α4 or VCAM-1 blocking antibodies effectively inhibit bone metastasis." (PMID 30930851, 2019). "Increased expression of VCAM1 in mammary tumor cells has been shown to induce bone lysis, resulting in the release of growth factors from bone that enable tumor cells to exit dormancy." (PMID 31819067, 2019). "In part, a recent study discovered that the recruited macrophages triggered the PI3K/Akt survival signaling pathway in newly disseminated breast cancer cells by engaging vascular cell adhesion molecule-1 (VCAM-1) via α4 integrins." (PMID 31300030, 2019). "Specifically, breast cancer cells that infiltrate leukocyte-rich microenvironments, such as the lungs, have a survival advantage when they overexpress VCAM-1." (PMID 31817646, 2019). "ATN-161 is a non–RGD peptide antagonist that blocks not only α5β1, but also αvβ3, significantly blunts macrophage activation, inhibits vascular cell adhesion protein 1 (VCAM-1) expression in atherosclerotic mice and reduces breast cancer metastasis." (PMID 31003546, 2019). "Both cell adhesion molecules ICAM-1 and VCAM-1 are increased in patients with advanced breast cancer and the increase in VCAM-1 is of prognostic significance." (PMID 31731625, 2019). "The shRNA-mediated knockdown of VCAM-1 in MDA231 breast cancer cells reduced adhesion with U937 promonocytic leukocyte cells, and also inhibited lung metastasis." (PMID 29614819, 2018). "Inhibiting the expression of VCAM-1 and integrin α4β1 would effectively suppress bone metastasis progression of breast cancer." (PMID 30456206, 2018). "It is also reported that MAMs suppress apoptosis of human breast cancer cells disseminated into the lung of mice by transmitting a survival signal via vascular cell adhesion molecule 1 (VCAM-1) on MDA-MB-231 human breast cancer cells." (PMID 30483271, 2018). "Osteoclast activity induced by receptor activator of nuclear factor kappa-Β ligand (RANKL) can also release dormant endosteal breast cancer micrometastases through vascular cell adhesion molecule 1 (VCAM-1) expression on the cancer cells." (PMID 30119678, 2018). "There are evidences indicating that VCAM-1 is upregulated in breast cancer cells and the VCAM-1 signaling networks involves in controlling EMT and chemoresistance in malignant breast tumors." (PMID 29301329, 2018). "Once in the lung parenchyma, metastatic breast cancer cells receive survival signals from MAMs through the interaction of vascular cell adhesion molecule-1 (VCAM-1) and α4-integrins." (PMID 29212030, 2017). "In a breast cancer bone metastasis dormancy model, it was shown that aberrant expression of vascular cell adhesion molecule 1 (VCAM-1) promoted the transition from indolent micrometastases to macrometastases." (PMID 27618899, 2016). "IL-13 which is derived from T-lymphocyte is highly expressed in breast cancer as reported in previous studies and exerts its effect by inducing the up-regulation of VCAM-1 which consequently modulates the angiogenesis event." (PMID 27558166, 2016).